MYD88 (MYD88 innate immune signal transduction adaptor)
Diseases named in the same sentence as MYD88 in open-access papers (continued):
Sharing a sentence is not in itself a finding about the gene and the disease.
lupus (continued). "These mice develop a disease that closely resembles Type III and Type IV lupus in humans, termed lupus nephritis, and this can be prevented by crossing the ABIN1[D485N] mice to MyD88 knock-out mice." (PMID 27133719, 2016). "In particular, B-cell intrinsic Myd88 plays a crucial role in autoimmunity, as lupus mice lacking Myd88 in B cells do not develop anti-nuclear antibodies (ANA) or rheumatoid factor (RF) formation." (PMID 34381449, 2021). "Importantly, these findings point to a defect in TBK1-dependent recruitment of signaling-competent MyD88 to autophagosomes, rather than a generalized defect in autophagy, which is in fact reported to be augmented in lupus-prone mice and human SLE B cells." (PMID 39060650, 2024). "Other studies reported that the inhibition of MyD88 dimerization by ST2825 blocked the induction of plasma cell differentiation and antibody production from the PBMC of systemic lupus erythematosus (SLE) patients." (PMID 35002734, 2021). "Among the MyD88-dependent TLRs—TLR7 and TLR9 are the prominent ones involved in the development of anti-DNA Abs in mouse models of lupus and altered TLR7 and 9 expression has been reported in human SLE patients as well." (PMID 31354738, 2019). "Also, BAFF and MyD88 signaling has been shown to promote lupus like disease independent of T cells." (PMID 20625435, 2010). "In MRL/lpr mice with TLR9K51E, a TLR9 point mutant lacking ligand binding, lupus was ameliorated compared to TLR9 knockout mice, which was ligand and MyD88 independent." (PMID 39960645, 2025). "Taking advantage of lupus-prone MRL.Faslpr mice in which MYD88 had been selectively inactivated in B cells, the investigators showed that self-reactive antibodies did not arise when MYD88 signaling was abrogated in B cells." (PMID 24106612, 2013).
COVID-19 (56 papers, 2020 to 2025). A disease caused by infection with severe acute respiratory syndrome coronavirus 2. "To conclude, TLR7 LOF mutations increase the risk of critical COVID-19 due to loss of viral RNA sensing ability and disrupted MyD88 signaling." (PMID 37567916, 2023). "Overall, COVID-19 severity appears to be similar in patients with MyD88/IRAK-4 deficiency and in those with TLR7 deficiency." (PMID 36880831, 2023). "Other genes commonly associated with COVID-19 immune responses (e.g., Stat1, Myd88, Il1b Nlrp3, Cdkn1a, and Casp1) were also upregulated in responder brains." (PMID 36739463, 2023). "We also searched for an enrichment in rare (gnomAD frequency <10−3) pLOF variants of IRAK4 and MYD88 in 3,269 patients with critical COVID-19, and 1,373 controls with asymptomatic or mild SARS-CoV-2 infection from the CHGE." (PMID 36880831, 2023). "Researchers found that TLR2 and MYD88 expression were both associated with the severity of COVID-19." (PMID 36575422, 2022). "-TLR2 and MyD88 are associated with the severity of COVID-19." (PMID 41011507, 2025). "TLR4 and its downstream signaling molecules, including CD14, MyD88, and TRAF6, are up-regulated in renal tubular and renal endothelial cells in COVID-19 patients, and are closely associated with acute tubular necrosis and increased kidney injury." (PMID 40584714, 2025). "However, the specific role of MyD88 in COVID-19-associated pain remains unclear." (PMID 40589538, 2025). "Studies have shown that the expression of TLR2 and its downstream MYD88 is correlated with COVID-19 severity and can sense the SARS-CoV-2 envelope protein to produce inflammatory cytokines." (PMID 38165854, 2024). "In summary, the Bayesian network analysis highlighted that specific signaling pathways, including interleukin signaling, MyD88:MAL signaling, TLR signaling, and innate immune response, are associated with the AUC in severe COVID-19." (PMID 37918965, 2024). "Although the dysregulation/overactivation of MyD88 is known to contribute to an exacerbated inflammatory response, the so-called “cytokine storm”, in COVID-19 patients, it is at least partly controlled by innate immune signaling." (PMID 39125989, 2024). "We found that the expression of MyD88 in both PBMCs and monocytes increased with the severity of COVID-19." (PMID 37310504, 2023). "Together, these data suggest an association of MyD88 and a panel of TLRs (i.e., TLR1, TLR2, TLR4, TLR5, TLR8, and TLR9) with disease progression in patients with COVID-19." (PMID 35682644, 2022). "In COVID-19, the TLR-4/MyD88 axis is activated and associated with the release of pro-inflammatory cytokines and the development of cytokine storm." (PMID 36114383, 2022). "A recent study shows that TLR2 and Myd88 are implicated in SARS-CoV-2-induced inflammatory response and are associated with COVID-19 disease severity." (PMID 35445287, 2022). "A possible stabilization of MYD88 in the presence of external stressors by statins could therefore suggest their role in protecting patients with COVID-19 from the development of an excessive inflammatory response." (PMID 40722786, 2025). "Higher expression of MAS-1 (MAS-1high) likely tracked IFhigh, as this signature comprised IF-related genes (e.g., C5AR1, MYD88) and higher baseline expression of MAS-1 associated with higherall-cause mortality hazards during acute COVID-19 as well as in the FHS." (PMID 37311745, 2023). "As will be demonstrated below, cytokine activation patterns in severe COVID-19 and its autoimmune complications invariably involve both the MyD88 and TRIF pathways simultaneously, suggesting roles for self- or bacterial antigens in addition to those presented by the SARS-CoV-2 virus." (PMID 36769320, 2023). "Interestingly, the increased expression of TLRs and MyD88 were found to be positively correlated with COVID-19 severity." (PMID 36650374, 2023).
COVID-19 (continued). "The bacterial infection phenotype of MyD88 or IRAK-4 deficiency is clearly recessive, but we analyzed possible co-dominance for the COVID-19 phenotype in 20 unvaccinated household relatives heterozygous for MYD88 or IRAK4 (mean age: 32.4 yr, SD: 12.3 yr, range: 10–52 yr)." (PMID 36880831, 2023). "Recent studies have shown that MYD88 participates in and influences the COVID-19 disease severity." (PMID 36414820, 2023). "It was found that the expression of TLR2 and MyD88 was related to the severity of COVID-19." (PMID 35935817, 2022). "In this work, we observed an overexpression of TLR2 and its coupled MyD88 adaptor in tracheal tissue from COVID-19/B.1.1.7 patients (p < 0.0001 vs. COVID-19/B.1 patients), while only MyD88 was overexpressed in COVID-19/B.1 variant (p = 0.0077 vs. control patients)." (PMID 36498845, 2022). "In this review, we aim to discuss the anti-inflammatory effects of irisin, focusing on the MAPK, AMPK, and TLR4/MyD88 intracellular pathways, and examine how exercise-induced irisin may improve the outcomes of inflammatory conditions, such as COVID-19." (PMID 35784579, 2022). "In terms of innate immunity, we showed that TLR2 and its adaptor MyD88 were overexpressed in tracheal biopsies of COVID-19 patients, which could contribute to the exaggerated inflammasome activation in COVID-19." (PMID 36498845, 2022). "Activation of TLR9 results in MyD88-dependent inflammatory signalling, which may be of some relevance in COVID-19 when host-derived DNA is released due to tissue damage or if there are opportunistic bacterial infections." (PMID 33505220, 2021). "Interestingly, this pathway with its components, TLR4, MyD88, and NF-κB, was pronounced in the overlay of the heme KG and COVID-19 KG." (PMID 33925394, 2021). "In mild cases of COVID-19, we further observed that the expression of PSMB8 in alveolar monocytes/macrophages was correlated with that of genes associated with the polarization of M1 macrophages, such as CD68, MYD88, and STAT1." (PMID 34225749, 2021). "As it has been observed that SARS-CoV infection can induce expression of the MyD88 gene, the ability of statins to maintain MyD88 at normal levels may be protective for patients with COVID-19." (PMID 33787678, 2021). "As such, therapeutic modulation of IRAK signaling, and perhaps also that of TLRs and MyD88, may be a useful strategy for treatment of patients with COVID-19." (PMID 34857794, 2021). "Given that overall imbalance in host immune system with inflammatory diseases including toxic shock, COPD as well as COVID-19 which is more to do with controlling inflammation, MyD88-targeted therapy would likely provide an advantage in treating severe inflammatory responses." (PMID 33834387, 2021). "Zheng and colleagues reanalyzed the expression of MyD88 and TLRs in patients with different severity grades of COVID-19 using a public dataset and found that the expression of MyD88, TLR1, TLR2, TLR4, TLR5, TLR8, and TLR9 was increased in patients with severe to critical illness." (PMID 34834939, 2021). "Therefore, we hypothesize that the specific inhibition of Gal3 and MyD88 may represent a promising therapeutic strategy for the treatment of COVID-19." (PMID 39125989, 2024). "Recent studies have found that the production of IL-1β, IL-18, TNF-α, and IL-6 was high in severe COVID-19 patients especially those with severe respiratory failure and are linked to the cytokine storm; these cytokines are downstream of the TLR4 canonical MyD88-dependent pathway." (PMID 33505220, 2021). "IL-33 activation has been reported in advanced COVID-19, contributing to severe lung inflammation by activating several proinflammatory cytokines such as IL-6 and TNF-α through the MyD88-MAPK-NF-kB signaling axis." (PMID 40242753, 2025).
COVID-19 (continued). "In COVID-19, TLR2 has been shown to be the primary innate sensor of the envelope protein of SARS-CoV-2, generating a cytokine response mediated via the MYD88 pathway with the subsequent activation of NF-κB and MAPK signalling." (PMID 36851206, 2023). "As observed in gene expression results, the expression of TLR2/MyD88 and NOX4/Nrf2 was also overexpressed in COVID-19 patients." (PMID 36498845, 2022). "In severe COVID-19, the transcriptome of whole blood shows more mRNA of several TLRs, including TLR2 and the TLR adaptor protein MyD88 in severe COVID-19." (PMID 35204803, 2022). "Parallel to the expression of MyD88, the expression of TLR1, TLR2, TLR4, TLR5, TLR8 and TLR9 was significantly elevated in patients with severe and critical COVID-19." (PMID 35682644, 2022). "As well as the macrophage-related genes MYD88 and STAT1, were upregulated in bronchoalveolar cells from patients with mild COVID-19, while cells from patients with severe COVID-19 were characterized by upregulation of the CD163 marker of M2 macrophages." (PMID 34225749, 2021). "Likewise, TLR4 and its downstream elements (including Myd88, IRAK1 and TRAF6, and NF-κB - dependent genes) were significantly upregulated in PBMCs from 20 human COVID-19 patients." (PMID 38439942, 2023). "To the best of our knowledge, we showed for the first time that all major populations of APC in blood are affected in COVID-19, and that the expression of key markers contributing to immune cell activation, including MyD88, NF-kB, and RANKL, are also impaired in COVID-19 patients." (PMID 33692788, 2021). "Most striking was the under-expression of genes involved in viral recognition (e.g. TLR7, UNC93B, RIG-I/DDX58), as well as genes encoding downstream signaling molecules and transcription factors (e.g. TRIF/TICAM1, MYD88, IRF7), with the notable exception of IRF4, in COVID-19 compared to INFL." (PMID 34135895, 2021). "Furthermore, the downstream factors of TLR7 and BTK in TLR pathway, such as MYD88, IRF7, NFKB1, and JUN, and cytokines (TNF, IL1B, and IL18) were elevated in men with severe COVID-19." (PMID 34330889, 2021). "Furthermore, the immunocomplex formation of TIRAP with MyD88, called myddosome, that is required for TLR4 signal transduction, was significantly higher in platelets from patients with COVID-19 compared with HS." (PMID 34092777, 2021). "In addition, patients with COVID-19 may develop a bacterial coinfection that releases LPS and activates the TLR4/MyD88 pathway." (PMID 35784579, 2022). "Thus, LXs through inhibition of TLR-4/MyD88, may reduce SARS-CoV-2-induced hyperinflammation and cytokine storm in COVID-19." (PMID 36114383, 2022). "To determine whether MyD88 or another TLR adapter, TRIF (TIR-domain-containing adapter-inducing interferon-β), plays a role in SARS-CoV-2-induced inflammatory responses, we analyzed mRNA expression of these factors in PBMCs and monocytes from patients with differing severity of COVID-19." (PMID 37310504, 2023). "Hence, through the negative modulation of the TLR4/MyD88 pathway, irisin could improve the condition of patients with COVID-19 and their outcomes." (PMID 35784579, 2022). "Dysregulation of MyD88 results in NF-kB activation that can increase lung damage, thus, statins preserve MyD88 at normal levels during infection and reduce NF-kB activation and it has been proposed that the modulation of TRL-MyD88 pathway by statins may be useful to treat COVID-19." (PMID 34778421, 2021).
ovarian carcinoma (56 papers, 2009 to 2025). A malignant neoplasm originating from the surface ovarian epithelium. "Research indicates that increased expressions of TLR4 and MyD88 are associated with diminished overall survival in ovarian cancer patients." (PMID 39390599, 2024). "Expression of TLR4 combined with MyD88 in epithelial ovarian cancer turned out to be independent risk factor for shortened survival time." (PMID 30976817, 2019). "TLR4/MD-2 complex-mediated MyD88-dependent activation of NF-κB and Akt promotes tumor-associated immunosuppression in epithelial ovarian cancer (EOC) via induction of immunesuppressive cytokines and indoleamine 2,3-dioxygenase (IDO)." (PMID 27118139, 2016). "Our findings suggest that miRNA-149 mediates the susceptibility of paclitaxel by regulating MyD88 expression in ovarian cancer cells." (PMID 26223974, 2015). "For example, we and others have already identified Toll-Like Receptor Signaling pathway modulator MyD88 as a CSC-regulator that is associated with poor prognosis in ovarian cancer patient samples." (PMID 25495823, 2014). "The TLR4/MyD88 pathway has in recent years been proposed as a risk factor for carcinogenesis and chemoresistance in ovarian cancer." (PMID 24977712, 2014). "Also, the TLR4/MyD88 signaling is implicated in the acquisition of paclitaxel resistance in ovarian cancer and MyD88 inhibition renders colon cancer cell lines susceptible to apoptosis mediated by cisplatin." (PMID 28662055, 2017). "In addition, high MyD88 expression was described in several tumors and enhanced levels of MyD88 were associated with poor prognosis in hepatocellular carcinoma, colorectal and ovarian cancers." (PMID 28662055, 2017). "Therefore miR-21 and miR-146a appear to be inversely linked to MyD88 in ovarian cancer." (PMID 24977712, 2014). "While secretion of IL‐12 which is influenced by the presence of MYD88, is indispensable in resisting T. gondii infection, it is not essential for eliciting an anti‐cancer response in instances of melanoma and ovarian cancer." (PMID 38109851, 2024). "Cells positive for CD44 and MyD88 in epithelial ovarian cancer demonstrated increased cytokine/chemokine production, an enhanced formation of spheroids, increased repair capacity, and chemoresistance." (PMID 38201468, 2023). "DAB2 expression had significant positive correlations with mesenchymal markers (ZEB2, TGFβ1, SNAI2, ZEB1, FN1, MMP2, TWIST1 and MMP3) and CSC markers (CD44 and MYD88) in ovarian cancer cell lines (CCLE) and tissues (TCGA: RNA sequencing and microarray)." (PMID 37815603, 2023). "Previously, we reported that different ovarian cancer cell types are derived from CD44+/MyD88+ EOC stem cells with lost stemness." (PMID 36123378, 2022). "Bclxl is upregulated in CD44+/MyD88+ chemoresistant ovarian cancer stem cells compared to CD44−/MyD88− sensitive ovarian cancer cells." (PMID 35565396, 2022). "While the molecular target of Cantrixil is yet to be confirmed, it has been identified as having potent cytotoxicity against chemoresistant CD44+/MyD88+ ovarian CSC clones and chemosensitive CD44-/MyD88- ovarian cancer cell lines." (PMID 34206826, 2021). "Cantrixil has shown broad cytotoxic activity against chemoresistant ovarian cancer stem cell (CD44+ MyD88+) populations in both 2D and 3D in vitro models, as well as potent cytotoxic activity against non-stem like ovarian cancer cells." (PMID 32532126, 2020). "In this study, we demonstrate a key link between senescence and inflammation and how this complex network involving the biomarkers MAD2, TLR4 and MyD88 drives paclitaxel resistance in ovarian cancer." (PMID 33370338, 2020). "To further explore the link between TLR4 and MAD2 we next analysed the expression of MAD2, TLR4 and MyD88 in 5 additional ovarian cancer cell lines; OVCAR-3, PEO1, OAW42, KURAMOCHI and 59M cells." (PMID 33370338, 2020).